HIF1A (hypoxia inducible factor 1 subunit alpha)
Diseases named in the same sentence as HIF1A in open-access papers (continued):
Sharing a sentence is not in itself a finding about the gene and the disease.
infection (continued). "For example, HIF-1α and HIF-2α as well as HIF-1α-specific and HIF-2α-specific target genes are increased at the site of murine L. major infection, but in vitro infection of macrophages with L. major does not induce HIF-1α expression." (PMID 40191198, 2025). "As similar to primary infection model, significant transcriptional activation of EPAS1, but not Hif1α, was observed in both LCLs." (PMID 38530845, 2024). "Thus, Hif1a conditional knockout in the myeloid lineage does not impact bacterial burdens or pathologic changes in bone architecture; however, trabecular BV/TV in VhlΔMyeloid mice is significantly lower at post-infection day 14 compared to the trabecular bone of Cre-negative littermate control mice." (PMID 36204648, 2022). "We observed a strong expression of HIF-1α upon LF82 infection in both conventional and gas-permeable cell culture dishes, indicating that hypoxia was not involved in LF82-induced HIF-1α expression." (PMID 33805299, 2021). "Infection of the murine mastocytoma cell line P815 with different IAV strains (human H1N1, avian H5N1 and H7N2) showed that HIF-1α was activated by H7N2 but not by H1N1 or H5N1, suggesting differing abilities of IAV strains to activate HIF-signalling pathways." (PMID 33113858, 2020). "Interestingly, direct infection of M(IL-4) macrophages with Mtb results in the establishment of aerobic glycolytic pathway and FM formation, which could be prevented by FAO activation or inhibition of the hypoxia-inducible factor 1-alpha (HIF-1α)-induced glycolytic pathway." (PMID 33002063, 2020). "We have previously reported that IRF-5-mediated inflammation was required to induce HIF-1α expression in dendritic cells and that this had an negative impact on their function and on CD8 T cell expansion during the first 10 days of infection." (PMID 32038622, 2019). "Consistently, under hypoxia, the infection of the wild-type EPEC E2348/69 strain induced the expressions of PDK1, PGK1, SLC2A1 (GLUT1), and PKM2, four well-defined HIF-1α targets, but did not induce the expression of SOD2, a well-defined HIF-2α target." (PMID 30125331, 2018). "Infection with HIF-1α shRNA lentivirus (HIF-1α-shRNA-1 and HIF-1α-shRNA-2) specifically prevented HIF-1α expression, but not HIF-2α expression, in RCC4 cells, which was further confirmed by detecting LDHA protein (a specific downstream target of HIF-1α)." (PMID 30125331, 2018). "Infection of cells with any of aCS3, VHL-aCS3, aNSa1 and VHL-aNSa1 did not result in changes in HIF1α protein levels, suggesting that the expression of the AdPROM system does not interfere with hypoxia signalling." (PMID 28490657, 2017). "The significant induction of Hif1a observed in A/J, but not in C57BL/6 mice, in response to infection, indicated more severe tissue hypoxia in the kidneys of infected A/J mice than in those of C57BL/6 mice." (PMID 28155859, 2017). "The 2-ME2 effect was specific to HIF-1α-induced PACAP38 expression, as it did not affect lentiviral (LV-PACAP38) infection-induced PACAP38 expression." (PMID 25523790, 2015). "However, unlike HIF-1α protein levels, which were markedly elevated in FLS under hypoxic conditions, HIF-2α protein showed only minimal accumulation under the same conditions; however, Ad-Epas1 infection under normoxic conditions caused marked expression of HIF-2α protein." (PMID 24914685, 2014). "The increased level of NO in non-infected embryos with stabilized Hif-1α indicates a priming of neutrophils to bacterial challenge, leading to greater levels of RNS pre-infection." (PMID 24367256, 2013). "Together, these data indicate that both HIF1α and GBP1 are involved in inflammasome activation in THP‐1 macrophages upon infection, although it may be independent of the nature of the infecting Mtb strain." (PMID 41287823, 2025).
infection (continued). "To determine if HIF1α plays a role in the innate immune transcriptional responses elicited by R. delemar in small airway epithelial cells, we performed RNA-seq analysis following 3 h of in vitro HSAEC1-KT infection in the presence or absence of LW6." (PMID 38902255, 2024). "Furthermore, we demonstrated that ACE2 expression in these cells was uncoupled from HIF-1α–mediated regulation, as indicated by the lack of change in ACE2 protein levels after PHD inhibition and/or infection." (PMID 37417946, 2023). "Limited expression of HIF-1α and IDO1 were observed regardless of infection status." (PMID 36989320, 2023). "Notably, HIF-1α is important for neutrophil survival in normoxia as well as hypoxia, and VEGFA and many other HIF-1α target genes, but not HIF1A itself, are upregulated following LVS infection including HK2, LDHA, PDK1 and SCL2A1." (PMID 35873156, 2022). "Interestingly, in the non-activated spheroids, Mtb-infection increased the percentage of IBA1, HIF1α-expressing and colocalizing cells, with significantly higher HIF1α-expressing cells, suggesting that Mtb-infected macrophages induce hypoxia." (PMID 34572395, 2021). "In addition, HIF-1α-specific and HIF-2α-specific target genes were examined with and without infection in BMDMs treated (or not) with DMOG." (PMID 34959539, 2021). "Furthermore, LF82 infection induced an increase in the mRNA expression level of VEGF, one of the well-known target of HIF-1α, but infection with LF82ΔPAI II or LF82ΔYbtE failed to do so." (PMID 33805299, 2021). "Indeed, AHA at concentrations of 20 mM during infection of AGS cells potently blocked enzyme activity, but did not suppress the ability of H. pylori to induce HIF-1α." (PMID 31185594, 2019). "The results showed that HIF-1α mRNA expression was not upregulated in either A549 or THP-1 cells infected with H1N1 compared with the non-infected controls, although the virus RNA levels increased with the infection dosage." (PMID 28536432, 2017). "As little as 2 h post invasion hif-1α transcript levels and those of a HIF-1α-target gene pfk2 were three- to fourfold higher in H-infected monocytes compared with non-infected monocytes indicating that infection had induced hif-1α transcription." (PMID 24112286, 2014). "However, in the absence of genetic perturbation of host HIF-1α, the possibility that hypoxia, CoCl2 or DMOG impact alternative pathways in the parasite that mediate the observed infection phenotype cannot be excluded." (PMID 24291761, 2014). "Thus, HIF1α is not required for general activation of NK cells during MCMV infection and may actually restrict NK activation early in infection." (PMID 34396954, 2021). "However, there were no HIF-1α-dependent differences in lung cytokine secretion, indicating that lung epithelial HIF-1α is not required to induce IL-1β, IL-6, CXCL1, CXCL2, or MIP-3α secretion during infection." (PMID 27624128, 2016).
bacterial infection (58 papers, 2010 to 2026). "Various reports are in line with our observations which suggested hosts deficient in HIF-1α are susceptible to bacterial infection." (PMID 35860264, 2022). "In contrast, loss of HIF-1α enhanced the pro-inflammatory activity of dendritic cells in a bacterial infection model." (PMID 33382742, 2020). "Loss of HIF-1α in macrophages results in impaired phagocytic uptake and killing capacity in diverse bacterial infection models." (PMID 31182997, 2019). "Additionally, these results indicate a novel role for HIF-1α as a susceptibility factor for systemic spread during K. pneumoniae infection and illustrate the complex interplay between pathogen and host molecules during bacterial infection." (PMID 27624128, 2016). "Because mice with deletion of HIF1A in the intestinal epithelium showed a significantly higher susceptibility to orogastric Y. enterocolitica infections, activation of HIF1A in host cells during bacterial infection represents a host defense mechanism in this study." (PMID 24086109, 2013). "Recent studies highlight that HIF-1α plays a key role in bacterial infections, with its activation being influenced by the type of pathogen and host factors." (PMID 40731804, 2025). "HIF-1α activation modulates the host response to bacterial infections by enhancing the transcription of genes involved in innate immunity, such as those encoding antimicrobial peptides, pro-inflammatory cytokines (e.g., IL-1β, TNF-α), and glycolytic enzymes." (PMID 40731804, 2025). "Apart from fungi, the importance of HIF-1α-mediated glycolytic response in Mφs was also observed in bacterial infection models, such as M. tuberculosis and L. monocytogenes." (PMID 39119289, 2024). "Future research should thus be warranted to investigate how pathogens have developed mechanisms to resist and adapt to HIF-1α-mediated immunity in Mφs, particularly in the context of chronic bacterial infection or re-infection models." (PMID 39119289, 2024). "In lung cancer, intratumoural bacterial infection burden was significantly correlated with HIF1A gene expression and hypoxia pathways." (PMID 38535967, 2024). "HIF-1α is an effective regulator of innate immunity that can inhibit the innate immune response of airway epithelial cells and promote bacterial infection, while P. aeruginosa secreted factors significantly inhibit its function." (PMID 38098038, 2023). "The results revealed that the expression of VEGFA decreased in HIF-1α knockdown cells compared to that in wild-type cells after bacterial infection." (PMID 36916939, 2023). "As the released HIF-1α in serum exosomes play an important role in tissue hypoxia after bacterial infection, the patterns of HIF-1α expression in serum exosomes through the course of the bacterial peritonitis episode within 72 h were investigated further." (PMID 34898382, 2022). "The need for activation of specific pathways that induce the EMT process during certain bacterial infections is maintained by intracellular ROS production and HIF-1a upregulation." (PMID 36613893, 2022). "Many studies have shown that HIF-1α can also be increased in response to bacterial infections in addition to (HIF-independent) hypoxia-sensitive pathways." (PMID 34898382, 2022). "HIF-1α is induced by bacterial infection and promotes the increase of phagocytosis and the release of antimicrobial peptides and granule proteases with direct microbicidal activity." (PMID 34898382, 2022). "In conclusion, HIF-1α is a global regulator of neutrophil inflammation and makes a role for anti-bacterial infection." (PMID 36761171, 2022). "HIF-1α is induced by bacterial infection and regulates the production of crucial immune effector molecules, including nitric oxide and TNF-α." (PMID 34898382, 2022). "Bacterial infections trigger hypoxia-induced host cell apoptosis and HIF-1α plays an important role in the process." (PMID 35860264, 2022).
bacterial infection (continued). "Overall, our findings demonstrate that MFN2 is a key coordinator of innate immune responses against intracellular bacterial infection through the maintenance of aerobic glycolysis and activation of xenophagy via HIF-1α." (PMID 33972668, 2021). "Although the underlying mechanism remains to be elucidated, this strongly suggests that NK cells can contribute to the control of bacterial infections in a HIF-1α-dependent manner, and this also involves direct killing of bacteria." (PMID 34349124, 2021). "Our results support an emerging concept of a role for HIF-1α in protection against bacterial infections." (PMID 34149713, 2021). "Our findings reveal the mechanistic regulations by which MFN2 tailors the innate host defense through coordinated control of immunometabolism and xenophagy via HIF-1α during bacterial infection." (PMID 33972668, 2021). "Our data suggest two overarching considerations regarding the mechanisms by which MFN2 contributes to innate host defense through coordination of immunometabolism and xenophagy via HIF-1α during intracellular bacterial infection." (PMID 33972668, 2021). "Our study should therefore encourage clinical studies to extend the clinical application of HIF-1α stabilizers for the treatment of severe bacterial infections." (PMID 34149713, 2021). "Herein we show that mitofusin-2 (MFN2), a mitochondrial fusion protein, promotes innate host defense through the maintenance of aerobic glycolysis and xenophagy via hypoxia-inducible factor (HIF)-1α during intracellular bacterial infection." (PMID 33972668, 2021). "In this study, we found that HIF1α-dependent glycolysis is important for M1 macrophage differentiation and plays a critical role in anti-bacterial infection." (PMID 32596169, 2020). "In response to macrophage stimulation by bacterial infection, lipopolysaccharides (LPS) or hypoxia, active NF-кB signalling triggers the activation of HIF-1α." (PMID 32228404, 2020). "It was found that HIF1α-dependent glycolysis is important for M1 macrophage differentiation and plays critical roles in anti-bacterial infection." (PMID 32596169, 2020). "HIF-1α also functions as an important regulator for myeloid cells against bacterial infection by producing antimicrobial peptides, TNF-α, and nitric oxide." (PMID 31885781, 2019). "In bacterial infections, enhanced abundance of HIF-1α promotes the antimicrobial capacity of phagocytes." (PMID 31036602, 2019). "Together, these data showed that HIF1α is required for pro-inflammatory macrophage differentiation during bacterial infection." (PMID 29483608, 2018). "Since LPS is a classic inducing factor for bacterial infection, this indicates that HIF1α is required for the differentiation of pro-inflammatory macrophages during bacterial infection." (PMID 29483608, 2018). "For LDHA, a minor increase was observed after 8 h of bacterial infection in cells expressing HIF-1α." (PMID 28401064, 2017). "In line with this notion, bacterial infection of macrophages under normoxic culture conditions results in robust stabilization of HIF-1α protein." (PMID 27034586, 2016). "The need of specific pathway activation for the induction of EMT-like processes in course of some bacterial infection is sustained by the production of intracellular ROS and HIF-1α upregulation." (PMID 26812644, 2016). "KLF2 inhibits monocyte activation by inhibiting NFκB activity, which correlates with decreased expression of multiple cytokines and HIF1α, a TF that regulates myeloid cell response to bacterial infection and reactive oxygen species." (PMID 25099603, 2014). "Previous reports on HIF1α's function during bacterial infection determined the importance of its activation and presence for neutrophil and macrophage-mediated pathogen killing." (PMID 25255025, 2014).
bacterial infection (continued). "A critical role of HIF-1α during bacterial infection was demonstrated in murine knockout studies showing that HIF-1α signaling is required for proper response to Streptococcal bacterial challenge." (PMID 24367256, 2013). "Three HIF-α isoforms have been identified in humans to date, of which HIF-1α is a key regulator of leukocyte function during both inflammation and a range of bacterial infections." (PMID 24367256, 2013). "NFκB is reported as the main contributor of HIF-1α transcription by LPS treatment or bacterial infection." (PMID 22701652, 2012). "Bacterial infection and LPS treatment increase HIF-1α expression by promoting transcription of HIF-1α; whereas, other inducers of HIF-1 like hypoxia, iron depletion or cobalt stabilize HIF-1α protein by decreasing prolyl hydroxylase activity." (PMID 22701652, 2012). "Furthermore, HIF1α activation in keratinocytes regulates production of anti-bacterial peptides and enhance defensive mechanisms for bacterial infection." (PMID 41576104, 2026). "Recent research highlights the pivotal role of HIF-1α in the context of bacterial infections." (PMID 40731804, 2025). "The transcription factor HIF-1α is expressed by activated neutrophils; it is targeted for degradation by oxygen-dependent propyl oxygenase but this enzyme is suppressed in response to bacterial infection and HIF-1α will therefore accumulate." (PMID 37048076, 2023). "The inhibition of HIF-1a is thought to be a novel strategy in treating bacterial infections." (PMID 36982790, 2023). "The high level of HIF-1α immunostaining in PI suggests that hypoxia may be the pathogenesis of peri-implant diseases and bacterial infection." (PMID 36013591, 2022). "HIF-1α-deficient (HIF-1α-/-) mice are susceptible to bacterial infection and have negative response to vaccine." (PMID 36761171, 2022). "A recent investigation has declared that STING could orchestrate metabolic reprogramming of macrophages via HIF-1α during bacterial infection." (PMID 35450066, 2022). "Our finding estimated that the changes expression in serum exosomes of HIF-1α during the early acute phase of bacterial infection might be potentially consistent with the elevated pro-inflammatory cytokine markers during the process of bacterial peritonitis." (PMID 34898382, 2022). "HIF-1α might have important temporal roles during bacterial infection, regulating the inflammatory response during the early acute phase." (PMID 34898382, 2022). "Hence, through HIF1α upregulation, the CS efficiently protects from bacterial infection by boosting innate immunity and hampering the switch to adaptive immunity." (PMID 33815383, 2021). "Finally, we asked to which extent the deletion of HIF-1α in NK cells alters the transcriptional programme in response to bacterial infections at a skin-wide level." (PMID 34349124, 2021). "Even though our results do not provide direct proof for a causative link between reduced cytokine release and p38 MAP kinase expression, we suggest that the “hypoxia-HIF-1α-p38 Map kinase axis” is a novel and intriguing target for host directed therapy of bacterial infections." (PMID 34149713, 2021). "Here we report that MFN2 promoted macrophage inflammatory signaling through optimal induction of aerobic glycolysis via hypoxia-inducible factor (HIF)-1α, which is activated by mitochondrial respiratory chain complex I and ROS, triggered by bacterial infection." (PMID 33972668, 2021). "HIF1α was shown to be upregulated in MC when cells mature or locate near a bacterial infection." (PMID 33815383, 2021). "Collectively, these data demonstrate a pivotal mechanism in the immunometabolic regulation of macrophages during B. abortus infection that is orchestrated by STING via HIF-1α pathway and highlight the metabolic reprogramming of macrophages as a potential treatment strategy for bacterial infections." (PMID 33989349, 2021). "In macrophages, the production of LPS by bacterial infection triggers glycolysis through HIF-1α." (PMID 32228404, 2020).